CCR2 (C-C motif chemokine receptor 2)
Diseases named in the same sentence as CCR2 in open-access papers (continued):
Sharing a sentence is not in itself a finding about the gene and the disease.
crescentic glomerulonephritis (3 papers, 2019 to 2021). A histopathologic term for a pattern of diseases characterized by extensive crescent formation in the glomeruli; patients present clinically with rapid deterioration of renal function, and possible progression to end-stage renal failure within weeks or months. "The ligation of CCR2 on podocytes stimulates their motility, with possible effects on the progression of crescentic glomerulonephritis." (PMID 34369383, 2021).
Crohn disease (3 papers, 2015 to 2023). A gastrointestinal disorder characterized by chronic inflammation involving all layers of the intestinal wall, noncaseating granulomas affecting the intestinal wall and regional lymph nodes, and transmural fibrosis. "Furthermore, CD14+CCR2+CX3CR1+ monocyte-derived intestinal MPs can elicit the activation of IFN-γ-producing CD3−CD56+NKp46+NKp44− group 1 ILCs from Crohn's disease patients." (PMID 26269452, 2015).
demyelination (3 papers, 2014 to 2020). "These series of experiments demonstrate the resistance of CCR2KO mice to sm-EAN suggesting a pathogenic role for CCR2 in acute peripheral nerve inflammatory demyelination." (PMID 24632828, 2014). "Indeed, we recently demonstrated in a mouse model of cortical demyelination that—in addition to conformation‐specific, anti‐myelin antibodies—peripheral immune cells including CCR2+ monocytes are crucial for demyelination." (PMID 31916298, 2020).
dengue (3 papers, 2010 to 2019). "Our major findings can be summarized as follows: 1) CCR1 does not seem to have a major role in the pathogenesis of severe experimental dengue infection; 2) CCR2 appeared to contribute to dengue-associated liver damage and this was reflected on decreased leukocyte activation and decreased lethality." (PMID 21206747, 2010). "More interestingly, plasmablasts and plasma cells had significantly higher frequencies of CXCR3 and CCR2 expression in dengue patients than healthy individuals." (PMID 30149800, 2018). "In the present work we have investigated the putative role of CC chemokine receptors CCR1, CCR2 and CCR4 in the context of experimental Dengue virus infection." (PMID 21206747, 2010). "Due to its various binding receptors such as CCR1, CCR2 and CCR5, CCL8/MCP-2 may have independent effects on immune response to dengue virus infection by engaging with different receptors to activate or suppress the effect of other chemokines." (PMID 30744623, 2019). "Recent clinical studies in endemic areas describe a correlation between dengue disease outcome and levels of CC chemokines, including CCL4/MIP1-β and CCL3/MIP1-α, both ligands for the CCR1 receptor, and for CCL2/MCP-1, the ligand for CCR2." (PMID 21206747, 2010).
diabetic neuropathy (3 papers, 2024 to 2025). A chronic, pathological complication associated with diabetes mellitus, where nerve damages are incurred due to diabetic microvascular injury involving small blood vessels that supply these nerves, resulting in peripheral and/or autonomic nerve dysfunction. "The ligands of chemokine receptors 2 and 5 (CCR2 and CCR5, respectively) are associated with the pathomechanism of neuropathic pain development, but their role in painful diabetic neuropathy remains unclear." (PMID 39000516, 2024). "Based on these results, we suggest that targeting CCR2 and CCR5 with CVC is a potent therapeutic option for novel pain treatments in diabetic neuropathy patients." (PMID 39000516, 2024). "It was proven that the blockade of CCR2 and CCR5, including the simultaneous blockade of both receptors by dual antagonists, effectively reduces hypersensitivity to thermal and mechanical stimuli in chronic pain states, including diabetic neuropathy." (PMID 39457105, 2024). "In mouse models of diabetic neuropathy, CCR2 spinal mRNA levels are not changed in female mice but they are reduced in male diabetic mice 7 days after STZ induction." (PMID 39457105, 2024).
ductal carcinomas (3 papers, 2019 to 2022). "Overall, these data indicated that ductal carcinomas with high CCR2 expression were associated with increased invasiveness and increased expression of CCL2, phospho-SMAD3 and phospho-p42/44MAPK." (PMID 33888841, 2021). "Compared to cells expressing control shRNAs, CCR2-KD cells showed a 50% decrease in CCR2 expression, compared to cells expressing control shRNAs, corresponding to decreased formation of invasive ductal carcinomas in mice." (PMID 31208996, 2019). "•CCR2 correlates with MET receptor expression in breast ductal carcinomas." (PMID 35405500, 2022).
emphysema (3 papers, 2020 to 2024). "recently demonstrated that the development of elastase-induced emphysema was dependent on the recruitment of Ly6Chi/CCR2+ monocytes using adoptive transfer studies and monocytes from wild type and CCR2-deficient mice." (PMID 38348034, 2024). "The central role of CCL2 and CCL7, and thus MoAM, in lung inflammation and pathology is corroborated by a strongly impaired recruitment of monocytes into the lung and protection from pulmonary emphysema upon inhibition of the CCR2/CCL2 axis." (PMID 38348034, 2024).
eosinophilia (3 papers, 2013 to 2022). "Reduced eosinophilia did not appear to be a direct effect of blockade of CCR2 signaling to eosinophils, because no CCR2 expression was detected on these cells during AAD (see Fig E6, C)." (PMID 33571538, 2021). "Our histological, histochemical, and flow cytometric analyses all support the notion that dexamethasone is effective in reducing eosinophilia without impacting the numbers of CCR2+ monocyte accumulation in the lung, resulting in beneficial effects on the trajectory of the disease." (PMID 35571100, 2022).
epileptic seizures (3 papers, 2009 to 2017). "Therefore, the relationship between the time points of MCP-1/CCR2 expression and KA-induced epileptic seizures needs further study." (PMID 28352122, 2017). "Seizures also resulted in alterations to the cell types expressing CCR2." (PMID 20034406, 2009). "We further investigated whether CCR-2, a chemokine receptor for MCP-1 that is reportedly involved in acute and chronic inflammation, participated in KA-induced epileptic seizures." (PMID 28386293, 2017). "To determine the detailed mechanisms of UR in KA-induced epileptic seizures, we investigated whether UR alters S100B, RAGE, mGluR3, MCP-1, and CCR-2 protein levels 6 weeks after KA injection." (PMID 28386293, 2017).
fungal infections (3 papers, 2012 to 2022). "CCR2-dependent monocyte recruitment plays an essential role in the control of several bacterial and fungal infections by inducing protective immune responses." (PMID 35585969, 2022). "Importantly, our results are the first report of a central role of the IFN-I-driven CCL2/CCR2 pathway in controlling inflammatory monocyte trafficking during fungal infections." (PMID 22911155, 2012).
kidney failure (3 papers, 2022 to 2025). An acute or chronic condition that is characterized by the inability of the kidneys to adequately filter the blood. "To test for a causal link between FMD-induced CCL2 decline, reduced renal monocyte recruitment, and kidney failure, we treated FMD or ad lib BALB/c male mice with a CCR2 inhibitor (CCR2i) after AA injection." (PMID 40755453, 2025).
kidney injury (3 papers, 2016 to 2025). Trauma to the kidney. "Of note, we also newly found that FMD reduced CCR2 expression on monocytes, which likely contributes to the reduced monocyte emigration from bone marrow after kidney injury." (PMID 40755453, 2025). "All of these results indicate that the MSC-derived exosomes may promote the recovery of I/R-induced kidney injury through a CCR2-dependent manner." (PMID 27843457, 2016).
latent infection (3 papers, 2019 to 2023). "For instance, CCL-2 was recently shown to mediate early seeding of the HIV reservoir by recruiting a unique subset of CCR2/5+ CD4+ T-cells which become infected and form a significant reservoir for latent infection." (PMID 36992409, 2023).
liver cirrhosis (3 papers, 2010 to 2025). "Our results indicate that pharmacological inhibition of CCR2 by CVC might become a key novel strategy for liver cirrhosis therapy without causing other organ injuries." (PMID 37215993, 2023).
Löfgren's syndrome (3 papers, 2010 to 2023). "Patients with Löfgren's syndrome may in fact constitute a disease entity by its own, and a recent report on specific associations between a CCR2 haplotype and Löfgren's syndrome support this hypothesis." (PMID 20187937, 2010).
lymph node metastasis (3 papers, 2016 to 2019). "Interestingly, 73% of patients who developed lymph node metastases had a high expression of CCR2, compared with only 27% of metastasis-positive patients having lower CCR2 expression." (PMID 30764543, 2019). "CCR2, CCR4, and their respective ligand-mediated pathways, CCR2\CCL2 axis and CCR4\CCL22 axis, are considered to be important mechanisms of lymph node metastasis." (PMID 31672162, 2019). "In this study, we found that CCR2 and CCR4 were highly expressed in Nav1.6 high-expression CRC tissues and were positively correlated with lymph node metastasis." (PMID 31672162, 2019).
lymphopenia (3 papers, 2010 to 2018). Reduction in the number of lymphocytes. "We also observed that lymphopenia was temporally associated with the upregulation of CCR2, LYN, PAK1, PTK2B, SRC, STAT3, which are involved in the chemokine signaling pathway." (PMID 30713538, 2018). "Therefore, the distorted proportion of naive versus activated/memory T cells in Ccr2 KO mice is primarily attributable to the homeostatic response induced by lymphopenia." (PMID 29930553, 2018).
malignant glioma (3 papers, 2020 to 2024). A grade III or grade IV glioma arising from the central nervous system. "The CCR2/CCL2 pathway is considered a relevant signal for the recruitment of TAMs and has been suggested as a therapeutic target in malignant gliomas." (PMID 32668709, 2020). "This is the first study showing that the suppression of the CCL2/CCR2 and CXCL10/CXCR3 axes by celecoxib may attribute to antitumor effects in a mouse malignant glioma model, in addition to intrinsic and extrinsic apoptotic induction by celecoxib in GSCs." (PMID 32943658, 2020). "Based on these findings, we hypothesized that in GSCs and a GSC-bearing malignant glioma model, modulation of the CCL2/CCR2 and CXCL10/CXCR3 axes by celecoxib might contribute to antitumor effects." (PMID 32943658, 2020).
metastatic melanoma (3 papers, 2022 to 2024). A melanoma that has spread from its primary site to another anatomic site. "Our data demonstrated that CD163+ TAMs accumulated in human metastatic melanoma display molecular phenotypes that strongly suggest they are derived from CD14+ CCR2+ monocytes." (PMID 38903497, 2024). "MDP treatment was ineffective in Nod2–/– and Ccr2–/– mice with established pulmonary metastatic melanoma colonies, demonstrating the necessity of I-NCMs in MDP-mediated tumor regression." (PMID 39545417, 2024).
muscular dystrophy (3 papers, 2014 to 2022). Muscular dystrophy (MD) refers to a group of more than 30 genetic diseases characterized by progressive weakness and degeneration of the skeletal muscles that control movement. "Since intramuscular MP accumulation and excessive skewing (in either direction) of the MP polarization balance have been implicated in muscular dystrophy pathogenesis, we next determined whether CCR2 deficiency affected the severity of muscle disease." (PMID 25312642, 2014). "To evaluate the role of CCR2 and its ligands in muscular dystrophy pathogenesis, we generated CCR2-deficient mdx mice (mdx-CCR2−/−)." (PMID 25312642, 2014).
neuropathic pain (3 papers, 2010 to 2024). Chronic pain caused by damage to nerve fibers. "Other studies have identified pharmacological interventions that prevent hyperalgesia development if CCL2 is neutralized prior to the neuropathic induction giving insight into an eventual CCR2-mediated treatment for neuropathic pain." (PMID 21143971, 2010). "Chemokines, including CCR2 and CCR5 ligands, have been demonstrated to have pronociceptive properties, and their levels are increased in CCI and STZ models of neuropathic pain." (PMID 39457105, 2024).
periodontitis (3 papers, 2023). An acute or chronic inflammatory process that affects the tissues that surround and support the teeth. "In our study, we observed that the levels of CCL2 and CCR2 were significantly decreased in StingGt periodontitis mice compared with WT periodontitis mice." (PMID 37405166, 2023). "Patients with periodontitis have been shown to have elevated numbers of CD14+ monocytes in the GCF —cells that demonstrate high expression of CCR2 and CCR5 compared to CD14− cells in the GCF." (PMID 38139161, 2023). "Our findings suggest that CCL2 and CCR2 may be involved in periodontitis progression by promoting macrophage recruitment, proinflammatory cytokine production and osteoclast formation." (PMID 37405166, 2023). "As expected, in contrast to untreated periodontitis mice, SR-717-treated mice had elevated CCL2 and CCR2 levels, while SN-011-treated mice had decreased levels." (PMID 37405166, 2023). "In addition, flow cytometry also showed significantly decreased chemokine (CCR2 and CCL2) levels in gingival tissues from periodontitis mice in the StingGt group in comparison with that in the WT group (p < 0.001)." (PMID 37405166, 2023). "Also overrepresented in disease was the chemokine receptor gene CCR2, which, along with its corresponding ligand CCL2, is known to be involved in monocyte recruitment and tissue destruction in various oral diseases, including periodontitis." (PMID 36883648, 2023).
pulmonary fungal infection (3 papers, 2014 to 2024). "In previous studies, we determined that CCR2+ monocytes are required to facilitate the activation of CD4+ T cell responses during pulmonary fungal infection." (PMID 39324785, 2024). "In previous studies, we observed that CCR2+ Ly6C+ monocytes are important precursors of mo-DCs that orchestrate the development of Th1 CD4+ T cell responses to pulmonary fungal infection." (PMID 29317510, 2018). "The role of CCR2+Mo-derived nitric oxide during pulmonary fungal infection remains undefined." (PMID 24586155, 2014).
pulmonary tuberculosis (3 papers, 2016 to 2025). A bacterial infection that affects the lungs and is caused by Mycobacterium tuberculosis. "Using a mouse model of pulmonary tuberculosis caused by the attenuated strain H37Ra, we methodically examined the function of the MCP-1/Ccr2 signaling axis in immunoregulation during MTB infection." (PMID 41562082, 2025). "We found that the combined loss of Ccr2 and Cx3cr1 also worsened Mtb control in the mediastinal lymph node, suggesting a rationale for the persistent expression of CX3CR1 among monocyte-derived cells in pulmonary tuberculosis." (PMID 40497732, 2025).
triple-negative breast carcinoma (3 papers, 2021 to 2024). An invasive breast carcinoma which is negative for expression of estrogen receptor (ER), progesterone receptor (PR), and human epidermal growth factor receptor 2 (HER2). "We examined associations of CCL2, CCR2, phospho-SMAD3 and phospho-p42/44MAPK with molecular subtype including: luminal A and B, HER2+ and triple negative breast cancers, which were identified using clinical guidelines on ER, PR, HER2 and Ki67/PCNA expression." (PMID 33888841, 2021).
type 1 diabetes (3 papers, 2017 to 2022). "Depletion of Akkermansia muciniphila has also been associated with mass translocation of endotoxin-activated CCR2+ monocytes, leading to pancreatic injury and type 1 diabetes (T1D)." (PMID 36558520, 2022).
ulcerative colitis (3 papers, 2023 to 2025). An inflammatory bowel disease involving the mucosal surface of the large intestine and rectum. "In contrast, cDC2 in aUC patients displayed lower expression levels of both CCR2 and CCR6 compared to those in quiescent ulcerative colitis (qUC) patients." (PMID 37893204, 2023).
ZIKV infection (3 papers, 2019 to 2026). "Moreover, ZIKV infection promoted pathogenic T cell infiltration into the CNS by enhancing the expression of chemokines for C-C motif chemokine receptor 2 (CCR2) in astrocytes, which was dependent on tumor necrosis factor receptor-associated factor 6 (TRAF6) signaling." (PMID 41403257, 2026). "Mice were treated with 10 mg/kg of CCR2 inhibitor one hour and 24 hours after ZIKV infection, followed by brain harvesting 48 hours post-infection." (PMID 40688087, 2025). "Prolonged CCR2 inhibition studies could help define its role in sustaining inflammation and microglial activation during chronic ZIKV infection." (PMID 40688087, 2025). "ZIKV infection, we compared the kinetics of ZIKV replication and clearance in CCR2+/+ and CCR2−/− mice." (PMID 31554802, 2019). "ZIKV infection, we did not detect a difference in viral control or clearance in CCR2+/+ and CCR2−/− animals." (PMID 31554802, 2019).
abscess (2 papers, 2013 to 2024). An inflammatory process characterized by the accumulation of pus within a newly formed tissue cavity which is the result of a bacterial, fungal, or parasitic infection or the presence of a foreign body. "By contrast to wild-type mice, CCR2−/− mice had almost fully recovered from the abscess lesions at seven days post-infection." (PMID 23300453, 2013). "Adoptive transfer of wild-type CD115+ monocytes into CCR2−/− mice restored abscess formation, and transferred monocytes were confirmed as mainly Ly6Chi-expressing cells." (PMID 23300453, 2013). "Thus, CCR2+Ly6Chi inflammatory monocytes appear to play a critical role in abscess formation." (PMID 23300453, 2013).
acute kidney injury (2 papers, 2022 to 2025). Sudden and sustained deterioration of the kidney function characterized by decreased glomerular filtration rate, increased serum creatinine or oliguria. "During sterile acute kidney injury CCR2+ monocytes drive lung capillary neutrophil retention." (PMID 40048367, 2025).
acute myeloid leukemia (2 papers, 2023 to 2026). Acute myeloid leukemia (AML) is a group of neoplasms arising from precursor cells committed to the myeloid cell-line differentiation. "In hematologic neoplasms, CCL2/CCR2 axis has been investigated in Acute Myeloid Leukemia (AML), multiple myeloma, and systemic mastocytosis." (PMID 37760903, 2023).
acute pancreatitis (2 papers, 2012 to 2022). An acute inflammatory process that leads to necrosis of the pancreatic parenchyma. "The increase in the CD68+CCR2+ population in the acute pancreatitis group at 24 hours favors the recruitment of these cells via CCL2/CCR2 axis into the lungs." (PMID 23110041, 2012). "Our data showed an enriched population of CD68+CCR2+ and CD68+CD206+ macrophages in the lungs in animals with acute pancreatitis." (PMID 23110041, 2012).
adenoma (2 papers, 2020 to 2024). A neoplasm arising from the epithelium. "In addition, there are two other significantly downregulated receptor genes, CXCR5 and CCR2, which both show a marked downregulation in adenoma samples." (PMID 39409185, 2024).
alcoholic liver diseases (2 papers, 2017 to 2020). A disorder caused by damage to the liver parenchyma due to alcohol consumption. "The expression of Gi-coupled receptors C-C chemokine receptor type 2 (CCR2), and C-C chemokine receptor type 5 (CCR5) is increased in the livers of patients with alcoholic liver disease (ALD)." (PMID 33076386, 2020).
and liver failure (2 papers, 2014 to 2024). "Together, these data indicate that CCR2 and CCR4 signaling are required for microglia activation and subsequent production of the proinflammatory cytokines IL-1β and IL-6 following AOM-induced liver failure." (PMID 25012628, 2014).